RGMB (repulsive guidance molecule BMP co-receptor b)
Description:
Member of the repulsive guidance molecule (RGM) family that contributes to the patterning of the developing nervous system (By similarity). Acts as a bone morphogenetic protein (BMP) coreceptor that potentiates BMP signaling (By similarity). Promotes neuronal adhesion (By similarity). May inhibit neurite outgrowth.
Synonyms: DRAGON; FLJ90406
Tractability: Small molecule: a structure with a bound ligand is known. Antibody: UniProt places it where antibodies can reach, with medium confidence; UniProt predicts a signal peptide or a membrane-spanning region; its Gene Ontology location is reachable by antibodies, with medium confidence. PROTAC: ubiquitination databases record sites on it; its protein half-life has been measured.
Gene: Protein-coding gene on chromosome 5 (98,768,004 to 98,798,643, forward strand). Ensembl gene ENSG00000174136.
Subcellular location: Cell membrane; Membrane raft
Subcellular location (Human Protein Atlas): Nucleoplasm
Pathways (Reactome):
Developmental Biology: Netrin-1 signaling
Gene Ontology:
Molecular function: protein binding; coreceptor activity; identical protein binding
Biological process: BMP signaling pathway; cell adhesion; positive regulation of DNA-templated transcription; signal transduction
Cellular component: endoplasmic reticulum-Golgi intermediate compartment; membrane raft; plasma membrane
Genetic constraint (gnomAD): Loss-of-function variants: 16 observed, 26.26 expected, observed/expected ratio (o/e) 0.61, 90% interval 0.41 to 0.93. The upper end of that interval is the gene's LOEUF score, 0.93, which puts it in group 3 of 6, group 1 being the genes least tolerant of losing a copy. Missense variants: 471 observed, 550.67 expected, observed/expected ratio (o/e) 0.86, 90% interval 0.79 to 0.92. Synonymous variants: 206 observed, 218.16 expected, observed/expected ratio (o/e) 0.94, 90% interval 0.84 to 1.06.
Homologues: Orthologues: chimpanzee RGMB (99% identical), macaque RGMB (97% identical), pig RGMB (92% identical), rabbit RGMB (92% identical), mouse Rgmb (89% identical), rat Rgmb (89% identical), guinea pig RGMB (87% identical), dog RGMB (80% identical), tropical clawed frog rgmb (73% identical), zebrafish rgmb (62% identical), Caenorhabditis elegans drag-1 (27% identical). Paralogues in human: RGMA (49% identical), HJV (42% identical).
Diseases named in the same sentence as RGMB in open-access papers:
RGMB is named in the same sentence as 31 diseases in open-access papers, as found by Europe PMC text mining. Sharing a sentence is not in itself a finding about the gene and the disease. The quoted sentences say what the papers report.
breast carcinoma (6 papers, 2015 to 2024). "Repulsive guidance molecule B (RGMB) has been shown to bind to PD-L2, which can promote T cell expansion and inhibit invasion and metastasis of bladder and breast cancer." (PMID 34178648, 2021). "While in breast cancer, RGMb and BMP signaling have a suppressive function, in colon cancer, RGMb has pro-oncogenic activities." (PMID 36153321, 2022).
colorectal cancer (6 papers, 2015 to 2025). A primary or metastatic malignant neoplasm that affects the colon or rectum. "The dysregulation of RGMB has been implicated in the development and progression of various malignancies in humans, including breast, prostate, lung, and colorectal cancers; melanomas, and osteosarcomas." (PMID 40538732, 2025). "RGMB represents a co-receptor for bone morphogenetic proteins, which was implicated in the angiogenesis and growth of colorectal cancer." (PMID 38049831, 2023).
inflammatory bowel disease (3 papers, 2021 to 2022). A spectrum of small and large bowel inflammatory diseases of unknown etiology. "To enhance our understanding of the molecular mechanisms of gut microbiota and inflammatory bowel disease (IBD), we studied the role of repulsive guidance molecule b (RGMb) in gut microbiota and colitis in mice." (PMID 33995306, 2021). "In order to understand how broadly RGMb might be involved in gut mucosal immunity, we assessed the impact of the BMP signaling pathway modulation in an inflammatory bowel disease (IBD) mouse model." (PMID 36420263, 2022).
lung carcinoma (3 papers, 2016 to 2024). "Our results also suggest that hypermethylation of the RGMB promoter is one mechanism underlying the downregulation of RGMB in lung cancer." (PMID 26910889, 2016). "RGMB expression was found to be significantly associated with lung cancer-associated mortality (P = 0.015)." (PMID 26910889, 2016). "In this study, we found that activation of PD-L2/RGMB pathway increased CCL20 expression to promote lung cancer progression." (PMID 39042313, 2024). "Blocking Smad1 in RGMB-knockdown A-549 cells diminishes the RGMB knockdown-enhanced migration of these cells suggesting that RGMB can inhibit the metastatic potential of lung cancer cells through suppression of the Smad-1/5/8 pathway." (PMID 26910889, 2016). "Because clinical stage is also a significant factor for prognosis, we further demonstrated the independent prognostic role of RGMB in early- and late-stage sub-groups of a cohort of lung cancer patients." (PMID 26910889, 2016). "The present study revealed that RGMB is downregulated in lung cancer and that downregulation of RGMB is correlated with poor prognosis and shorter OS." (PMID 26910889, 2016). "Electric cell substrate impedance sensing (ECIS) and wounding assays showed that the ability of the lung cancer cells to attach and migrate was enhanced by RGMB knockdown." (PMID 26910889, 2016). "Suppression of RGMB promoted metastasis, thereby providing mechanistic insight into the role of RGMB in lung cancer development." (PMID 26910889, 2016). "We first evaluated RGMB expression in lung cancer cell lines." (PMID 26910889, 2016). "However, the role of RGMB in lung cancer metastasis is unclear." (PMID 26910889, 2016).
osteosarcoma (3 papers, 2019 to 2025). A usually aggressive malignant bone-forming mesenchymal neoplasm, predominantly affecting adolescents and young adults. "We, therefore, investigated what roles RNF4, BMP6, and RGMb play in osteosarcoma and melanoma cancer cells." (PMID 36153321, 2022). "Here, we report that RNF4 via BMP6 and RGMb is required for tumor cell survival and tumorigenicity of osteosarcoma and RTK inhibitor-resistant melanoma cells (A375R)." (PMID 36153321, 2022). "Taken together, our data suggest that RNF4 and its downstream target genes, BMP6 and RGMb, are essential for the survival of osteosarcoma and RTKi-resistant melanoma cells and that RNF4 and BMP6 may serve as markers associated with poorer prognosis in sarcomas." (PMID 36153321, 2022). "Furthermore, BMPR2, RGMb, and neogenin were detected in osteosarcoma cell lines by WB." (PMID 30886151, 2019). "The expression levels of BBRN supercomplex (RGMb, BMPR2, and Neo1) in the primary and metastatic osteosarcoma tumors were evaluated by IHC, and the results indicated BBRN supercomplex expression was increased in lung metastases compared with primary osteosarcoma." (PMID 30886151, 2019). "Since RGMb is present on the surface of hBMSCs and BMP6 is a secreted factor, we used naturalizing antibodies to each of these factors and tested for inhibition of proliferation and formation of tumor spheres of osteosarcoma U-2-OS cells and melanoma A375R cells." (PMID 36153321, 2022).
prostate carcinoma (3 papers, 2015 to 2019). A carcinoma that arises from epithelial cells of the prostate gland. "In prostate cancer, the knockdown of RGMB significantly enhanced the prostate cancer cell capacity, namely increased growth, adhesive, motility and mobility." (PMID 26055877, 2015). "BMP co-receptor repulsive guidance molecule b (RGMb) was upregulated in vascular endothelial cells after hepatocyte growth factor (HGF) stimulation, which was combined with BMP-7 to induce angiogenesis in breast and prostate cancers." (PMID 27661009, 2016).
colitis (2 papers, 2021 to 2022). Inflammation of the colon. "The present study investigated the effect of anti-RGMb blocking antibody on experimental colitis induced by dextran sulphate sodium (DSS) in C57BL/6 mice, with the aim to characterize the colonic inflammatory response at the cellular and molecular level." (PMID 36420263, 2022). "It remains unclear exactly how the inflammation in the gut of mice with colitis is reduced by RGMb blockade; however, we observed that in DSS-treated mice, the colon length was reduced in the isotype and not the 9D1 treated animals." (PMID 36420263, 2022).
glioma (2 papers, 2019 to 2022). A benign or malignant brain and spinal cord tumor that arises from glial cells (astrocytes, oligodendrocytes, ependymal cells). "RGMB, EDN1, SEMA3C and NRTN have been indicated to regulate olfactory neurogenesis, mesenchymal stem cells regeneration, tumorigenicity of glioma stem cells and neurite outgrowth, respectively." (PMID 35511361, 2022).
Anxiety (1 paper, 2020). Intense feelings of nervousness, tension, or panic often arise in response to interpersonal stresses. "TCF4 is a phenotype seed gene for DD, ID, ASD, speech delay, GI problems, dental, Pes planus, hypotonia, and facial dysmorphisms; NFIA is a phenotype seed gene for anxiety, GI problems, and hypotonia; and RGMB appears as a phenotype seed gene for ASD." (PMID 33282601, 2020).
autoimmune disease (1 paper, 2019). A disorder resulting from loss of function or tissue destruction of an organ or multiple organs, arising from humoral or cellular immune responses of the individual to their own tissue constituents. "Our data suggest that the interaction surface between RGMB and sCTLA-4 presents a novel therapeutic target for both autoimmune diseases and tumors, especially in cases where systemic alteration of CTLA-4 induces adverse effects." (PMID 31061392, 2019).
glioblastoma (1 paper, 2025). The most malignant astrocytic tumor (WHO grade IV). "RGMB is overexpressed in glioblastoma and promotes tumor growth and invasion." (PMID 40608798, 2025).
head and neck squamous cell carcinoma (1 paper, 2021). A squamous cell carcinoma that arises from any of the following anatomic sites: lip and oral cavity, nasal cavity, paranasal sinuses, pharynx, larynx, and salivary glands. "MiR-93-5p enhances migration and invasion in head and neck squamous cell carcinoma through targeting RGMB." (PMID 34130593, 2021).
injury (1 paper, 2019). Damage inflicted on the body as the direct or indirect result of an external force, with or without disruption of structural continuity. "OPG, RGMB, and ROBO2 have been implicated in CNS development, axonal growth, and recovery after nerve injury, whereas upregulation of brevican has been observed in the CNS during the consolidation of long-term memories." (PMID 31694701, 2019).
iron overload disease (1 paper, 2020). "The two RGMB mutations Gly101Arg and Leu103Glu correspond to RGMC mutations that cause the blood iron overload disease juvenile hemochromatosis." (PMID 32576689, 2020).
lung adenocarcinoma (1 paper, 2025). A carcinoma that arises from the lung and is characterized by the presence of malignant glandular epithelial cells. "So far, we initially found the targeting relationship of PRKCQ-AS1/miR-582-3p regulatory axis and its target genes (STXBP6, RGMB) in lung adenocarcinoma cells." (PMID 40597380, 2025). "Dual luciferase reporter assay demonstrated the presence of miR-582-3p in PC-9 lung adenocarcinoma cells in relation to STXBP6 and RGMB target binding." (PMID 40597380, 2025).
non-small cell lung carcinoma (1 paper, 2016). A group of at least three distinct histological types of lung cancer, including non-small cell squamous cell carcinoma, adenocarcinoma, and large cell carcinoma. "We evaluated repulsive guidance molecule B (RGMB) expression in 165 non-small cell lung cancer (NSCLC) tumors and 22 normal lung tissue samples, and validated the results in an independent series of 131 samples." (PMID 26910889, 2016).
Obesity (1 paper, 2023). Accumulation of substantial excess body fat. "PCSK9, MST1, and RPS6K1 predominantly mediated the detrimental effect of sedentary behavior on CAD, while the effect of smoking was mainly mediated by RGMB, PCSK9, ITPKA, RPS6KA1, and AGER, which partially aligned with the observed association pattern between obesity and CAD." (PMID 38049831, 2023).
osteoarthritis (1 paper, 2025). A noninflammatory degenerative joint disease occurring chiefly in older persons, characterized by degeneration of the articular cartilage, hypertrophy of bone at the margins and changes in the synovial membrane. "Research on the role of RGMB in ThumbOA has not been reported to date, but we infer two reasons why RGMB may serve as a therapeutic target: First, osteoarthritis is usually accompanied by vascular invasion, and neurogenesis and vasculature are linked through common pathways." (PMID 39932908, 2025).
pneumonitis (1 paper, 2023). An inflammatory process affecting the lung parenchyma. "A previous study has reported that the competitive binding of PD-1 antibody to PD-L2 can disrupt the normal function of PD-L2 and other binding partners, leading to the activation of RGMb (repulsive guidance molecule) and subsequently cause pneumonitis." (PMID 37520574, 2023).
sarcoma (1 paper, 2022). A usually aggressive malignant neoplasm of the soft tissue or bone. "However, given the role of BMP6 and RGMb as survival factors in sarcoma, these experiments should also address a potential transformation/tumor-promoting aspect of these factors, as they may be a “double adage sord”." (PMID 36153321, 2022). "Thus, suggesting that the pro-tumorigenic activity of RNF4 is multifaceted and that the RNF4-RGMb-BMP6 pathway acts primarily as a pro-survival pathway in sarcomas and therapy-resistant cells, and that BMP6 and RGMb inhibition has a potent anti-cancer activity." (PMID 36153321, 2022).
tumor (11 papers, 2014 to 2025). "Through binding to PD-L2, RGMB promotes colorectal cancer growth and facilitates tumor metastasis and invasion in osteosarcoma." (PMID 39042313, 2024). "Intriguingly, the expression of RGMb was markedly increased in tumor‐infiltrating CD8+ T cells, but not other immune cells, in anti‐tumor immune responses resistance mice, and its anti‐tumor effect was confirmed by conditional knockout of RGMb in T cells." (PMID 37789962, 2023). "attempted to determine the role of RGMb, another identified PD‐L2 binding protein, in promoting anti‐tumor immune effects to ICIs." (PMID 37789962, 2023). "More recently, the interaction between PD and L2 on tumor cells and repulsive guidance molecule B (RGMb) on macrophages was observed that prevented macrophage-mediated tumor cell killing." (PMID 35035479, 2022). "Our results revealed that the expression level of miR-93-5p was upregulated in tumor samples, and the expression of RGMB was upregulated in normal samples." (PMID 32328191, 2020). "We further found that expression levels of RGMB negatively correlated with various hallmarks of immune activation in tumor tissues, including the expression of CTL effector molecules." (PMID 31061392, 2019). "Our study establishes a Tumor Microenvironment-derived Prognostic Model (MPM) that integrates eight TME-associated genes (CXCL12, GZMB, ITPR2, LYN, RAB9B, RGMB, RUFY4, TRIM16) to stratify AML patients into distinct risk categories with significant survival differences." (PMID 40608798, 2025). "However, it is worth noting that the role of RGMB in tumor progression remains controversial because both inhibitory and promoting functions have been reported in various experimental systems." (PMID 39042313, 2024). "Additionally, we identified RGMB as a direct target of miR-93-5p and demonstrated that RGMB is essential for mediating the tumor-promoting effects of miR-93-5p in SCCHN cells." (PMID 32328191, 2020). "Luciferase reporter assays were used to demonstrate that miR-93-5p directly targeted the 3' UTR of RGMB, and we further found that the tumor-promoting functions of miR-93-5p were partly mediated by targeting RGMB, whose downregulation also promoted the migration and invasion of SCCHN." (PMID 32328191, 2020). "Therefore, we next investigated the roles of RGMB in anti-tumor immunity." (PMID 31061392, 2019). "RGMB is expressed by different cell types and may contribute to tumor growth and progression." (PMID 26910889, 2016). "Altogether, our findings show that expression levels of RGMB negatively correlate with multiple hallmarks of immune activation, such as CTL effector gene expression and abundance of activated T cells, in tumor tissues." (PMID 31061392, 2019). "However, augmentation of sCTLA-4 activity is expected to be a major mechanism for RGMB to suppress anti-tumor immunity, as it was shown that the negative correlation between RGMB expression and CTL activity in tumor tissues was more evident with higher levels of sCTLA-4." (PMID 31061392, 2019).
cancer (7 papers, 2016 to 2024). A tumor composed of atypical neoplastic, often pleomorphic cells that invade other tissues. "Microbiota dysbiosis causes the upregulation of PD-L2 and its receptor RGMB on CD8+ T cells, thus explaining the resistance of cancers to PD-L1 blockades." (PMID 39791702, 2024). "Despite these previous findings, studies examining the role of RGMB in cancer metastasis and EMT remain scarce, particularly those related to SCCHN." (PMID 32328191, 2020). "Mechanismly, PD-L2 bound its receptor Repulsive guidance molecule B (RGMB) on cancer cells and activated extracellular signal-regulated kinase (Erk) and nuclear factor κB (NFκB), leading to increased production of chemokine CCL20, which recruited Tregs and contributed to NSCLC progression." (PMID 39042313, 2024). "Likewise, RGMb is a new player in cancer biology and has both anti- and pro-tumorigenic activities that are cancer-type-dependent." (PMID 36153321, 2022). "Conversely, RGMB overexpression and secretion suppressed cancer progression." (PMID 26910889, 2016). "RGMB expression levels negatively correlated with CD8 T cell abundance (25 of 33 cancers, p = 0.003), as well as with activated memory CD4+ T cells (26 of 33 cancers, p = 0.001)." (PMID 31061392, 2019). "The activation of Smad-1/5/8 observed in RGMB knockdown cells could have resulted in transcriptional regulation of BMP-responsive genes, and enhanced invasion and migration of cancer cells." (PMID 26910889, 2016). "Taken together, our study highlights the important roles of RNF4 and its regulated factors RGMb and BMP6 in osteogenic differentiation of mesenchymal stem cell and cancer opening the door for the development of diagnostics and specific inhibitors for the treatment of these challenging cancers." (PMID 36153321, 2022). "Potential alterations in RGMC/HFE2/HJV also are present in different cancers, but as with RGMA and RGMB, the possible functional consequences have not been determined." (PMID 30746893, 2019). "Given that we demonstrated that RGMB specifically supports the suppressive activity of sCTLA-4, we next investigated to what extent the amount of sCTLA-4 affected the negative correlations observed between RGMB expression and CTL activity in various cancer tissues." (PMID 31061392, 2019).
RGMB also shares sentences with these, for which no sentence is quoted: colon cancer (2 papers); melanoma (2); ovarian carcinoma (2); Alzheimer disease (1); esophageal squamous cell carcinoma (1); juvenile hemochromatosis (1); mastitis (1); pancreatic carcinoma (1); squamous cell carcinoma of the (1).